Y_RNA (Y RNA )
Gene: Miscellaneous RNA gene on chromosome 16 (178,554 to 178,656, forward strand). Ensembl gene ENSG00000207243.
Homologues: Orthologues: chimpanzee Y_RNA (95% identical), pig Y_RNA (71% identical). Paralogues in human: Y_RNA (83% identical), Y_RNA (81% identical), Y_RNA (80% identical), Y_RNA (79% identical), RNY3 (78% identical), Y_RNA (78% identical), RNY3P1 (77% identical), Y_RNA (77% identical), Y_RNA (76% identical), Y_RNA (75% identical), RNY3P14 (74% identical), Y_RNA (74% identical), and 92 more.